CASP2 (caspase 2)
Diseases named in the same sentence as CASP2 in open-access papers (continued):
Sharing a sentence is not in itself a finding about the gene and the disease.
tumor (continued). "Taken together, this suggests that the transcriptional upregulation in HCC tumors observed for CASP2 and PIDD1 is directly linked to the higher proliferation rates in the tumor while the expression of RAIDD is uncoupled from the proliferative state." (PMID 33225610, 2020). "Ultimately, it is unlikely that cleavage of MDM2 represents the sole mechanism of tumor suppression by caspase-2." (PMID 33425918, 2020). "As such, tumor cell density can serve as an independent prognostic marker, while CASP2 mRNA expression serves as a surrogate of the proliferative capacity of tumor cells comparable in paucity to the well‐established proliferation marker Ki67." (PMID 33225610, 2020). "Deletion of caspase-2 increased tumor incidence and significantly decreased cancer free survival in multiparous female mice." (PMID 33425918, 2020). "Caspase-2 is considered a pro-apoptotic caspase that has a unique role as a tumor suppressor in multiple tissue types." (PMID 33425918, 2020). "The implication of caspase-2 in death-receptor-mediated apoptosis is very efficient in tumor cells than normal wild type cells both in vivo and in vitro." (PMID 32438737, 2020). "Caspase-2 has been identified as a tumor suppressor in multiple murine models of oncogene-driven cancers." (PMID 33425918, 2020). "Recent studies suggest that caspase-2 mediates its tumor suppressor function by inducing senescence and/or apoptosis of aneuploid cells." (PMID 30670683, 2019). "Since aneuploidy and chromosomal instability is a characteristic feature of caspase-2−/− tumors in mice, apoptosis of aneuploidy cells is considered as a major tumor suppressive activity of caspase-2." (PMID 31366165, 2019). "Our study has identified specific caspase-2 expression signatures in the different tumor types that likely contribute to the distinct tumor outcomes." (PMID 30670683, 2019). "Our recent findings have also demonstrated that the tumor suppression function of caspase-2 is context specific." (PMID 30670683, 2019). "Overall, our study has identified new genes and pathways that contribute to the caspase-2 tumor suppressor function and highlight distinct roles for caspase-2 in different tissues." (PMID 30670683, 2019). "Consistent with this, reduced expression of Camk2a and Camk2b was validated in different EμMyc/Casp2−/− tumor samples." (PMID 30670683, 2019). "Significant downregulation of Casp2 was also verified in the EμMyc/Casp2−/− comparison and Casp2 gene deletion was confirmed by genotyping and immunoblotting in all tumor samples." (PMID 30670683, 2019). "The cross-tumor-specific transcriptional aberrations are highly indicative of distinct roles for caspase-2 during neuronal and B-cell development that perhaps influence its tumor suppressor function." (PMID 30670683, 2019). "Correspondingly, a decrease in caspase-2 expression was evidently shown in several types of human cancers, thus, indicating a tumor suppressive role of caspase-2." (PMID 31366165, 2019). "CASP2 (caspase-2) is reported to mediate tumor suppression as an initiator of survivin gene silencing." (PMID 30589909, 2018). "Despite recent achievements implicating caspase-2 in tumor suppression, the enzyme stands out from the apoptotic caspase family as a factor whose function requires further clarification." (PMID 29362422, 2018).
tumor (continued). "The correlative observations indicating a role for caspase-2 in human malignancies are supported by experimental evidence in mouse models of tumours." (PMID 27906175, 2016). "On the basis of its reported proapoptotic properties, caspase-2 is considered to act as a tumor suppressor." (PMID 27049919, 2016). "Compelling evidences suggest a tumor suppressive activity of caspase-2, eventually independently of its effect on cell death." (PMID 25114039, 2014). "In particular, during these last years compelling evidence support an important tumor suppressive role of the caspase-2." (PMID 25114039, 2014). "The original results described here demonstrate that this tumor suppressive activity of caspase-2 is mediated, at least in part, by its pro-senescing activity." (PMID 25114039, 2014). "This strongly supports that the tumor suppressive activity of the caspase-2 is largely mediated by its ability to promote senescence." (PMID 25114039, 2014). "Caspase-2 deletion only slightly accelerated tumour development in mice expressing the c-neu oncogene in mammary cells and failed to alter cancer incidence following irradiation or exposure to 3-methylcholanthrene." (PMID 27919034, 2014). "In conclusion, the ability of TAp73alpha to act as an inhibitor of caspase-2-induced cell death together with its up-regulation in certain tumour types strengthen the potential oncogenic activities for this protein." (PMID 22201672, 2011). "However, since mouse caspase-2 expressed in the tumor cells cannot be activated by the HUHS015 series of compounds, humanized mice with agonist-competent caspase-2 need to be generated." (PMID 38676703, 2024). "Caspase-2 is widely recognized as a tumor-suppressive protein due to its role in apoptosis." (PMID 39625520, 2024). "For example, it is unclear whether caspase-2 could also inhibit autophagy in tumor cells and whether this biological effect of caspase-2 is critical for tumor suppression." (PMID 39543123, 2024). "A great deal of studies has shown the involvement of caspase-2 as a tumor suppressor in multiple oncogene-driven cancers, and yet a comprehensive understanding of its biological roles remains largely unknown." (PMID 36171196, 2022). "Several in vivo studies underscore the relevance of caspase-2 in tumor suppression." (PMID 35444189, 2022). "Indeed, caspase-2 functions as a tumor suppressor in a number of mouse models driven by different oncogenic activators in both hematological malignancies and solid tumors." (PMID 35741016, 2022). "Despite its involvement in several cellular processes and identification as a tumor-suppressor in multiple oncogene-driven cancers, a clear functional role of caspase-2 remains unknown." (PMID 36171196, 2022). "Since transcriptional control has a delayed effect on cellular events compared to that of protein level regulation, the activation of caspase-2 bears a more substantial effect on long-term tumor survival than on the outcome of acute cell death in the studied tumor cells." (PMID 35444189, 2022). "The reason for this discrepancy is unclear, but as the severity and timing of diethylnitrosamine-induced tumor appearance is dependent on many factors, the rate of HCC development may have masked the effects of caspase-2 deficiency." (PMID 33854186, 2021). "The same trends were observed for transcript levels of Casp2 and Pidd1 in tumor tissue (Fig EV2A)." (PMID 33225610, 2020). "In this review, we highlight the substrates of caspase-2 and explore possible mechanisms of substrate selection that may regulate the tumor suppressive function of caspase-2." (PMID 33425918, 2020). "Identifying the mechanism of this increased proliferation could reveal the mechanism of tumor suppression by caspase-2." (PMID 33425918, 2020).
tumor (continued). "Interestingly, a study showed that upon the downregulation of PKCK2, TRAIL-mediated apoptosis of tumor cells was orchestrated by caspase-2 via the processing caspase-8." (PMID 32438737, 2020). "Determining if BID cleavage is defective in these models would be valuable in determining the true mechanism of tumor suppression by caspase-2 as it would suggest that apoptosis is impaired in these tumors, even though it may be masked in vivo." (PMID 33425918, 2020). "Although there are few clear examples of an apoptotic defect in caspase-2 deficient tumor models, BID cleavage has not been examined in these models." (PMID 33425918, 2020). "Uniquely, caspase-2 has been identified as a tumor suppressor, but how it regulates this function is still unknown." (PMID 33425918, 2020). "The mechanism of tumor suppression by caspase-2 has been difficult to determine." (PMID 33425918, 2020). "Rather, we provide a discussion of the more well-studied caspase-2 substrates, with attention paid to how these substrates may be executing the functions of caspase-2 that could contribute to tumor suppression." (PMID 33425918, 2020). "Somewhat unique among the caspase family is caspase-2’s proposed function as a tumor suppressor." (PMID 33425918, 2020). "While caspase-2 deficiency alone is not competent to induce tumor formation, its role as a tumor suppressor has been recapitulated by independent groups and in various cancer models." (PMID 33425918, 2020). "More remarkably, genetic inhibition of caspase-2 by siRNA suppresses apoptosis of tumor cells induced by genotoxic insults such as etoposide, cisplatin, and 5-fluorouracil (5-FU) in tumor cells and DNA enzyme (DZ13) induced caspase-2 activation has also been implicated in tumor suppression." (PMID 32438737, 2020). "In spite of the fact that the precise molecular mechanisms of caspase-2 activation in tumor suppression remain unclear, growing evidence emphasizes that caspase-2 has a significant role in this aspect." (PMID 32438737, 2020). "This is not the only model where caspase-2 has been implicated in tumor progression rather than suppression." (PMID 33425918, 2020). "Because cleavage of BID is a well-established contributor to apoptosis, BID proteolysis could be a potential mechanism to explain tumor suppression by caspase-2." (PMID 33425918, 2020). "Genomic instability is a hallmark of cancer, and is thought to promote tumor heterogeneity and overall tumor survival, so this could also be a potential mechanism to explain the tumor suppressor function of caspase-2." (PMID 33425918, 2020). "Ultimately, the true contribution of apoptosis to the mechanism of tumor suppression by caspase-2 is still largely unknown." (PMID 33425918, 2020). "Again, this shows that caspase-2 has an important role in protection from aberrant cell cycling, which could be critical for its ability to suppress tumor formation." (PMID 33425918, 2020). "Paradoxically, PIDDosome-independent tumor suppressor function of caspase-2 has been reported." (PMID 32438737, 2020). "Furthermore, in colorectal cancer reduced CASP2 expression is caused by loss of its transcriptional regulator BCL9L, and is a key cause of aneuploidy tolerance, tumor progression, and resistance." (PMID 30670683, 2019). "Caspase-2 is a highly conserved cysteine protease with roles in apoptosis and tumor suppression." (PMID 30670683, 2019). "Functionally, the HuR dependent inhibition of caspase-2 translation could, furthermore, constitute an important rescue mechanism of adenocarcinoma cells protecting tumor cells from DNA damage-induced apoptosis." (PMID 31366165, 2019).
tumor (continued). "Correlative evidence supports a tumor suppressor function for caspase-2." (PMID 30670683, 2019). "Accordingly, caspase-2 harbors tumor-suppressing properties following oncogenic pressure." (PMID 29362422, 2018). "Whether the observed Caspase-2 tumor suppressor function in this context requires the PIDDosome and how this relates to the increased hepatocyte ploidy described here need to be addressed experimentally." (PMID 28130345, 2017). "Caspase-2-deficient mice have a near normal phenotype and do not develop excessive tumors with aging, despite the fact that caspase-2 is an inhibitor of apoptosis and as such, might have some tumor suppressing functions." (PMID 26890135, 2016). "Furthermore, caspase 2 has been increasingly seen as a tumour suppressor, being able to influence many tumour-promoting activities." (PMID 25300915, 2015). "Overall, these data demonstrate that the adaptor protein Raidd is not limiting Myc-driven tumorigenesis thereby uncoupling the tumor-suppressor function of Caspase-2 from Raidd-dependent autoactivation and the oncogenic potential of Pidd1 from Raidd-modulated NF-κB signaling." (PMID 25857265, 2015). "Additionally, caspase 2 has been attracting a great deal of research attention since its activation was found to induce apoptosis in many tumour cells." (PMID 25300915, 2015). "The role of Caspase-2 as a tumor suppressor and that of Pidd1 as a tumor promoter can therefore be uncoupled from their ability to interact with the Raidd scaffold, pointing toward the existence of alternative signaling modules engaging these two proteins in this context." (PMID 25857265, 2015). "Further studies with cells from caspase-2 −/− mice have indicated that caspase-2 could be considered a tumor suppressor, since its absence can favor oncogene-mediated transformation." (PMID 25330190, 2014). "It has been suggested that nuclear casp-2 might play a role in tumor suppression by functioning in DNA damage signaling." (PMID 23840868, 2013). "Recent studies have indicated that in addition to acting as an initiator caspase, caspase-2 plays an important role in cell-cycle checkpoint regulation and tumor suppression as well as DNA-damage induced expression of p21 possibly through enhanced translation of the protein." (PMID 23596516, 2013). "Interestingly, the tumor suppression effect of caspase-2 in the mouse requires an active catalytic site." (PMID 23596516, 2013). "Casp2 has been implicated in apoptotic and non-apoptotic processes such as cell cycle regulation, tumor suppression and aging (Bouchier-Hayes and Green 2012 for review)." (PMID 23504374, 2013). "In particular CASP2, JNK2, PDCD10, and ST13 have been associated with mitochondrial permeabilization and with the induction of the apoptotic process, while SPARC overexpression seems to play a tumor suppressor function in some low expressing SPARC AMLs." (PMID 24148231, 2013). "Furthermore, in an E mu-Myc mouse model of lymphomagenesis, loss of caspase-2 results in an increased ability of cells to acquire a transformed phenotype and become malignant, indicating that caspase-2 functions as a tumour suppressor." (PMID 22201672, 2011). "Caspase-2 has also been reported to exert tumour suppressor function in vivo." (PMID 22201672, 2011). "Thus, the ability of TAp73alpha to inhibit caspase-2 induced cell death and its up-regulation in certain tumour types uncover new potential oncogenic activities for this protein." (PMID 22201672, 2011). "Beyond regulating development, the miRNAs described here may also have important consequences for cancer, as both Casp2 and Ei24 are considered tumor suppressors." (PMID 21573140, 2011).
tumor (continued). "Notably, our findings reveal that caspase-2 roles in tumor suppression and hepatosteatosis control are separable and demonstrate that long-term inhibition of caspase-2 catalytic function disrupts the liver polyploid balance that augments liver pathophysiology and tumorigenesis." (PMID 41477850, 2026). "Based on these published data and the results presented thus far; we hypothesized that SAC-targeting drugs activate CASP-2 in tumor cells and ultimately trigger CASP-3 mediated apoptosis or aneuploidy/polyploidy and survival, the balance between the two outcomes being determined by BID levels." (PMID 37443114, 2023). "Interestingly, both caspase-2 and caspase-8 have been shown to play a tumor-promoting role." (PMID 35741016, 2022). "In addition, experiments using caspase-2 null mice showed that this enzyme might act as tumor suppressor via its ability to eliminate cells with chromosomal perturbations or after mitotic insults." (PMID 36171196, 2022). "Similarly, loss of RAIDD does not phenocopy the effects of loss of caspase-2 on tumor suppression since RAIDD deficiency had no impact on Eμ-Myc-induced lymphomagenesis." (PMID 33425918, 2020). "However, there is limited information as to whether BID phenocopies the tumor suppressive properties of caspase-2." (PMID 33425918, 2020). "However, many of these experiments were done using a C-terminally tagged version of Ku80, so further investigation is needed to determine if the tag impacted the cleavage of Ku80 and to see if this occurs physiologically and promotes the tumor suppressor effect of caspase-2." (PMID 33425918, 2020). "Caspase-2 is the most evolutionarily conserved member of the mammalian caspase family and has been implicated in both apoptotic and non-apoptotic signaling pathways, including tumor suppression, cell cycle regulation, and DNA repair." (PMID 32438737, 2020). "Importantly, in clear contrast to RKO cells, overexpression of TRIM25 in HEK cells had no comparable effects on caspase-2 levels, suggesting that the negative regulation of caspase-2 by TRIM25 could probably reflect a tumor-specific phenomenon." (PMID 31842382, 2019). "Thus, the tumour suppressor function of caspase 2 may become a new option in therapeutic strategy aimed at control of tumour growth under a high level expression of HMGA2." (PMID 25300915, 2015). "Caspase-2 knock-out mice develop normally and are viable, while the absence of caspase-2 expression in the presence of an oncogenic signal led to the formation of aggressive tumours in immunodeficient mice, suggesting that this particular caspase is a tumour suppressor protein." (PMID 23404198, 2013). "Furthermore, the posttranslational regulations associated with Hu Antigen R (HuR) which connects to the enhanced translation of tumor-promoting genes, such as Cyclin D1, or the decreased translation of tumor-suppressing genes, such as caspase 2, are altered by overexpressing MCT-1." (PMID 23211466, 2012). "miR-483-5p overexpression was demonstrated to promote tumor growth in PCa cells by suppressing RBM5, a tumor suppressor gene that modulates apoptosis by regulating the alternative splicing of critical apoptotic mediators, including FAS and caspase-2." (PMID 41136394, 2025). "For example, inhibition of Chk1 in human tumor cells triggers hyperactivation of ATM, ATR, and caspase-2, leading to apoptosis after DNA damage." (PMID 39861152, 2025). "Data from our own laboratory revealed that in addition to controlling the transcriptome of tumor cells, TRIM25 affects post-transcriptional regulation of the pro-apoptotic caspase-2 and caspase-7 via different mechanisms." (PMID 39851496, 2025). "Thus, caspase-2 may function as a potential tumor suppressor." (PMID 38676703, 2024).